CRP (C-reactive protein)
Diseases named in the same sentence as CRP in open-access papers (continued):
Sharing a sentence is not in itself a finding about the gene and the disease.
infection (continued). "Among septic non-cancer patients there is substantial controversy concerning the potential effects of immunosuppression, in particular of corticosteroids, on CRP concentration, decreasing acute phase response independently of the treatment of infection." (PMID 21595932, 2011). "Only one participant had a CRP level > 10 mg/L, a level suggested as an indicator of infection, suggesting that most of the participants did not have recent infections before the blood draw." (PMID 21628108, 2011). "In cases where the CRP continued to rise after postoperative days 5–7, a new antibiotic was used for the presumptive infection." (PMID 21427784, 2011). "The majority of these studies have evaluated biomarkers in combination with CRP because CRP is already in widespread clinical use for the diagnosis of infection." (PMID 23198120, 2011). "On the other hand, infection by bacteria containing GlcNAc will induce the CRP:L-ficolin mediated amplification pathway: GlcNAc→CRP:L-ficolin→C1→C4→C2→C3." (PMID 21283780, 2011). "Several potential biomarkers of infection have been assessed in the evaluation of febrile neutropenic patients, like interleukin (IL)-6, IL-8, serum amyloid A, C-reactive protein (CRP), procalcitonin, with diverse results." (PMID 21595932, 2011). "It is recognised that the porcine APP response to infection is typically characterised by elevations in serum levels of C-reactive protein as the major APP." (PMID 20140096, 2010). "Both these results demonstrate that, despite CRP has been repeatedly shown to be a sensitive marker of infection; it predicts poorly the patient outcome." (PMID 20875120, 2010). "Findings in this patient including recrudescence of fever, rising CRP levels and neutrophilia were consistent with a secondary infection despite being treated with broad-spectrum antibiotics." (PMID 20540811, 2010). "C-reactive protein (CRP) is an acute reactant protein that is increased under conditions of infection, trauma, tissue necrosis, tumor, and several types of inflammatory disease." (PMID 20465852, 2010). "Cytokines rise quickly after infection even in neonates, and are more sensitive to low concentrations of pathogens than CRP." (PMID 20231868, 2010). "Our study showed that the detectable levels LBP, IL-6 and CRP differ in the earl stage of infection dependent on severity of infection." (PMID 20158885, 2010). "A CRP of 4.6 mg/l had a sensitivity of 79 and a specificity of 68% to detect infection of spine implants." (PMID 20179760, 2010). "C-reactive protein despite being a sensitive marker of infection, it predicts poorly the patient outcome." (PMID 20875120, 2010). "We show here that the AUC of the NLCR ROC curve was significantly higher than that of conventional infection markers, including the CRP level." (PMID 21034463, 2010). "In this line of evidence, one of the most studied proteins is C-reactive protein (CRP), an acute-phase reactant protein that increases in response to different stimuli, like inflammation or infection." (PMID 21804778, 2010). "C-reactive protein (CRP) is among those factors which are produced by liver within 8 to 12 hours after infection or inflammation." (PMID 22577410, 2010). "C reactive protein (CRP) is an indicator of immune activation in response to inflammatory damage or infection and has been shown to increase in HIV-1–infected individuals." (PMID 21776340, 2010). "Single CRP measurement can be influenced by many factors such as infections, stress, timing of measurement and lab error." (PMID 19400931, 2009). "One of these markers, C-reactive protein (CRP), is produced by the liver in response to tissue injury or infection." (PMID 20512289, 2009). "Previous studies have presented doubtful conclusions regarding the efficiency of CRP for differentiating infection from inflammation, especially during the postoperative period." (PMID 20512289, 2009).
infection (continued). "This is further supported by its rapid elevation in infection, and the fact that the CRP, ESR and WCC are still elevated during this period." (PMID 22505973, 2009). "As well as the major increases in expression of CRP in response to infection or tissue injury, minor elevation in CRP levels has been recognised as a possible marker of disease in systemic conditions." (PMID 19732183, 2009). "Standard laboratory variables such as CRP have a slow kinetic profile rendering it an inappropriate marker for a fast evaluation of the dynamics of an infection." (PMID 19493352, 2009). "Since AGP concentrations remain raised for longer after infection than other acute phase proteins such as CRP and haptoglobin, AGP has been used as a marker of sub-clinical infection in large scale human studies." (PMID 20042096, 2009). "Circulating at low concentrations in healthy individuals, CRP rises dramatically in response to infection, inflammation, and injury." (PMID 22505974, 2009). "Within SBI+ve cases, s-TREM-1 was significantly higher in infections other than IPD compared to IPD, and CRP was significantly higher in IPD compare to infections other than IPD." (PMID 19675669, 2009). "C-reactive protein (CRP) is an acute phase protein, the levels of which increase rapidly in the circulation during infection and/or inflammation." (PMID 19545442, 2009). "Considering the importance of distinguishing inflammatory septic response from non-infective events, this study had the aim of evaluating the role of CRP as a marker for infection in critically ill patients during the postoperative period." (PMID 20512289, 2009). "Procalcitonin (PCT) and C-reactive protein (CRP) are established markers of infection in the general population." (PMID 19291300, 2009). "Other studies confirm that an elevated CRP serves as a systemic marker of focal inflammation and infection." (PMID 19878592, 2009). "To confirm this, we reconstituted the healthy serum with 10 μg/ml CRP (acute phase level) and adjusted the pH and calcium to infection-inflammation condition." (PMID 19180241, 2009). "To delineate the mechanisms of complement enhancement by infection-inflammation, we focused on the CRP and ficolins, two pH- and calcium- sensitive components of the complement system." (PMID 19180241, 2009). "C-reactive protein (CRP) is commonly used as a marker for inflammatory states and for early identification of infection." (PMID 20512289, 2009). "Taken together, our findings explain why and how a typical infection-inflammation condition provokes crosstalk between CRP and the L-ficolin, which boosts the complement system." (PMID 19180241, 2009). "Whenever there is an infection or tissue inflammation, interleukin-6, interleukin-1β, and tumor necrosis factor-α stimulate hepatocytes to synthesise CRP." (PMID 20011658, 2009). "This study aimed to investigate CRP as a marker for infection in patients with postoperative septic shock." (PMID 20512289, 2009). "The acute inflammatory response is induced by numerous challenges to the body, including infections and trauma, and leads to gross changes in the levels of CRP and other acute phase proteins." (PMID 19732183, 2009). "In critically ill children, PCT has been found to be a better marker of infection as compared to CRP and leucocyte count." (PMID 20011658, 2009). "• In chronic critically ill patients PCT performs better than other widely used infection markers, such as CRP and WBC count." (PMID 20028533, 2009). "To demonstrate how infection-inflammation condition triggers the interaction between CRP and ficolins, we examined their binding characterisitics over a range of pH 5.5 to 7.4 under either 2 mM or 2.5 mM calcium." (PMID 19180241, 2009). "The complement system is a major microbicidal force in the infection-inflammation condition mediated by the synergistic effect of CRP and ficolins." (PMID 19180241, 2009).
infection (continued). "We propose that CRP interacts with L-ficolin under infection-inflammation condition, enhancing the complement-activated killing of the P. aeruginosa." (PMID 19180241, 2009). "Regarding the primary outcome of proven infection, PCT performed better than other widely used infection markers, such as CRP and WBC count, in this population of patients." (PMID 20028533, 2009). "Since C3-deposition is the pivotal step towards the formation of the MAC, we sought to detect C3 deposition on the bacteria by incubating P. aeruginosa with whole serum, or serum depleted of CRP or ficolin in the healthy or infection-inflammation conditions." (PMID 19180241, 2009). "CRP levels in normal (n = 5) and patient sera (n = 9) were measured and patients with acute phase infection recruited in this study typically showed serum CRP level of 10 μg/ml, which was used in subsequent experiments." (PMID 19180241, 2009). "C-reactive protein (CRP) is a representative marker for inflammatory conditions, and performs a crucial anti-infection function in the immune system." (PMID 19457231, 2009). "ProET-1 levels significantly correlated with other biomarkers of infection, i.e. procalcitonin (r2 = 0.31, p < 0.0001), C-reactive protein (r2 = 0.11, p < 0.0001) and total leukocyte count (r2 = 0.07, p < 0.001)." (PMID 18304365, 2008). "CRP iscommonly used as a marker of an acute inflammatory state, produced by the liverin response to tissue injury or infection." (PMID 18385816, 2008). "Accordingly, this study supports the use of CRP as an indicator of possible infection in the elderly with the same cut-off values as in younger adults." (PMID 18706087, 2008). "CRP is synthesized by the liver, mainly in response to IL-6, which is produced not only during infection but also in many types of inflammation." (PMID 19578505, 2008). "Rintala and co-workers showed that CRP levels peak between 24 and 48 h after admission for an infection." (PMID 18957115, 2008). "Other authors suggest thatSAA is a more sensitive marker than CRP in infections with low inflammatory activity (including manyviral infections) and in other clinical conditions, especially those involvingthe lung tissue." (PMID 18385816, 2008). "If that were the case, patients on steroid therapy would have a blunted acute-phase response with very low levels of CRP in response to an infection." (PMID 18547407, 2008). "CRP was measured as a marker of infection and to detect its confounding effect on serum ferritin level." (PMID 18312681, 2008). "The initial or acute phase response of the immune system to infection or other stressors involves the release of cytokines such as C-reactive protein (CRP)." (PMID 18704199, 2008). "Many studies have evaluated the usefulness of various markers of infection in different septic conditions – C-reactive protein (CRP), procalcitonin (PCT), TNFα, and IL-6, IL-8, and IL-10." (PMID 17598889, 2007). "Inthe present study, the patients were clinically free of infection, and C-reactive protein levels in most of thepatients were normal or only slightly increased." (PMID 18274646, 2007). "Barring recent infections, changes in disease state, or stress, CRP baseline concentrations are reported to be relatively steady with minimal diurnal or seasonal variation." (PMID 19690638, 2007). "The mean of PCT was significantly higher in the group with severe infection (6.7 ng/mL versus 0.6 ng/mL – p = 0.0075) comparing with CRP." (PMID 18034890, 2007). "On the other hand, in septic patients – in whom we assume that infection is the main factor inducing CRP production – CRP levels can quickly drop after successful treatment." (PMID 17598889, 2007). "C-reactive protein (CRP) is produced by the liver as part of the ‘reorchestration’ of hepatic gene expression in response to inflammation and infection." (PMID 19690638, 2007).
infection (continued). "When these results were seen in the light of the accuracy and predictive value indices, CRP again reaffirmed its position as a good predictor of infection on both the second and the fifth postoperative days." (PMID 17505683, 2007). "In clinical practice, CRP is the most accessible and widely used marker of infection, and many authors have addressed its sensitivity and specificity, some of whom compared CRP levels among various diagnoses and/or severities of organ dysfunction." (PMID 17598889, 2007). "Some studies evaluated the value of some serum markers of infection, such as C-reactive protein (CRP) and interleukins, in monitoring the response to antibiotic treatment." (PMID 17723153, 2007). "Lobo and colleagues found that increased CRP concentrations were associated with organ failure, prolonged ICU stay and high infection and mortality rates." (PMID 17723153, 2007). "Levels of all studied inflammatory markers (HMGB1, LBP, PCT, IL-6) and infection markers (C-reactive protein, white blood cell count, neutrophils) were elevated among bacteraemic patients." (PMID 17625012, 2007). "Baseline CT-proET-1 values of all patients demonstrated a significant correlation with other markers of infection, i.e., procalcitonin (r =.39, p < .05) and CRP (0.35, p < .05), and with mean blood pressure (r =−.25, p < .05)." (PMID 18080871, 2007). "Out of all the variables studied, CRP was the most important acute-phase protein for predicting postoperative infection." (PMID 17505683, 2007). "Many studies have evaluated the usefulness of various markers of infection, including C-reactive protein (CRP), which is the most accessible and widely used." (PMID 17598889, 2007). "We have previously shown that C-reactive protein (CRP) and IL-6 were better markers for infection than soluble haemoglobin scavenger receptor (sCD163) in a population of patients prospectively admitted to a department of internal medicine." (PMID 17346334, 2007). "Patient 6 had a positive imaging study with a CRP level of only 5.3, attesting to the limited extent to which traditional blood tests can be used to assess infection." (PMID 17925855, 2007). "PCT and CRP levels were significantly higher in neutropenic febrile patients with infection than in control patients (P < 0.001)." (PMID 18034890, 2007). "A recent study evaluated 49 children, who had 60 febrile episodes compared follow-up value of PCT with CRP in documenting the infection in neutropenic febrile patients." (PMID 18034890, 2007). "With these cut off levels CRP and IL-6 have sensitivities higher than 58% and specificities greater than 88% in diagnosing infection." (PMID 16569262, 2006). "Using a cut off level of 30 mg/l, CRP had a sensitivity of 80.2% and a specificity of 62.7% in diagnosing infection." (PMID 16569262, 2006). "The AUC of the maximum daily CRP variation as a predictor of infection was 0.86 (95% confidence interval: 0.752–0.933)." (PMID 16635270, 2006). "ProADM levels correlated with other biomarkers of infection, that is, procalcitonin (r = 0.51, p < 0.001), and to a lesser degree with CRP (r = 0.16, p < 0.01), and total leukocyte count (r = 0.23, p < 0.001)." (PMID 16805922, 2006). "The plasma half-life of CRP is about 19 hours and seems to be constant whatever the disease; this means that the sole determinant of CRP level is the synthesis rate, which can be sustained after infections complicating trauma or surgery." (PMID 16569261, 2006). "• In a cohort of patients with less severe community-acquired infections, CRP, IL-6 and LBP appear to be superior to PCT as diagnostic markers for infection." (PMID 16569262, 2006). "Elevated CRP levels are seen in infection, in autoimmune disease, in cancer, in trauma and in surgery." (PMID 16569262, 2006).
infection (continued). "We have previously shown that CRP and IL-6 are better markers of infection and severity of infection than soluble hemoglobin scavenger receptor (sCD163) in a population of patients admitted to a Department of Internal Medicine." (PMID 16569262, 2006). "The area under the curve for the maximum daily CRP variation in infection prediction was 0.86 (95% confidence interval: 0.752–0.933)." (PMID 16635270, 2006). "An increase in CRP >4.1 mg/dl was a marker of infection prediction with a sensitivity of 92.1% and a specificity of 71.4% (positive likelihood ratio 3.22, negative likelihood ratio 0.11)." (PMID 16635270, 2006). "In that study, performed with critically ill patients, a 25% or greater increase in the CRP concentration from the previous day's level was highly suggestive of infection." (PMID 16635270, 2006). "The multivariable logistic regression analysis found that only the maximum daily CRP variation was an independent predictor of infection (model n = 63, 35 of which developed infection; AUC = 0.899, goodness-of-fit = 0.593)." (PMID 16635270, 2006). "Within individuals, CRP levels are also correlated with the number of seropositivities to common pathogens, suggestive of infection history." (PMID 15904534, 2005). "An increased C-reactive protein level is part of the acute-phase response to most forms of inflammation, infection, tissue damage, and malignant neoplasia." (PMID 16117833, 2005). "Using this method,CRP was assayed as a means of monitoring for infection in newborns up to 72 h after delivery." (PMID 18924835, 1998). "Similarly, her WBC, lactic acid, and procalcitonin levels, markers of infection, were within normal limits, but her CRP remained elevated." (PMID 42011450, 2026). "In the specific context of DF, CRP has been widely used as a marker of infection severity." (PMID 41601759, 2026). "The CRP/ESR ratio helps distinguish the presence of infection in patients with SLE." (PMID 41972130, 2026). "Persistent elevation of CRP may indicate failure to control infection and systemic inflammation, and it has been proposed as a parameter for assessing patient safety." (PMID 41573125, 2026). "The infection group presented a higher bp-SUVr (4.63 ± 1.68) compared to neoplasia (4.38 ± 1.89) and other conditions (3.43 ± 2.19), while CRP levels were distinctly elevated in infection (15.29 ± 4.11 mg/L) vs. neoplasia (4.86 ± 1.56 mg/L) and other (4.43 ± 3.21 mg/L)." (PMID 41594176, 2026). "Regular assessments of clinical response, laboratory tests (e.g., CRP and white blood cell count), and radiological imaging are necessary to evaluate the resolution of infection and identify any potential complications, such as the development of an abscess or sequestrum." (PMID 41497025, 2026). "All biomarkers could be used to distinguish infection with CRP (AUROC 0.77; 95% confidence intervals [CI] 0.70-0.83) and procalcitonin (AUROC 0.75; 95% CI 0.68-0.81) showing fair performance." (PMID 42069535, 2026). "Implementing slower and personalized titration schedules based on the patient’s ancestry and factors impairing clozapine metabolism (e.g., infections and comedication) while performing baseline and weekly CRP assessments can substantially increase the safety of clozapine use worldwide." (PMID 41567753, 2026). "If CRP is normal at baseline and becomes abnormal during titration, this is a possible sign for either clozapine‐induced inflammation (CAM being the most common form), which is associated with too‐rapid titration or another concurrent infection." (PMID 41567753, 2026). "They found that Hs-CRP had the highest diagnostic performance, with an AUC of 0.91 and an optimal cut-off of 3.47 mg/dL, yielding 80% sensitivity and 89% specificity—superior to both procalcitonin and WBC count—indicating that Hs-CRP has greater clinical value for infection detection." (PMID 41601759, 2026).